PCK1 (phosphoenolpyruvate carboxykinase 1)
Description:
Cytosolic phosphoenolpyruvate carboxykinase that catalyzes the reversible decarboxylation and phosphorylation of oxaloacetate (OAA) and acts as the rate-limiting enzyme in gluconeogenesis. Regulates cataplerosis and anaplerosis, the processes that control the levels of metabolic intermediates in the citric acid cycle. At low glucose levels, it catalyzes the cataplerotic conversion of oxaloacetate to phosphoenolpyruvate (PEP), the rate-limiting step in the metabolic pathway that produces glucose from lactate and other precursors derived from the citric acid cycle. At high glucose levels, it catalyzes the anaplerotic conversion of phosphoenolpyruvate to oxaloacetate. Acts as a regulator of formation and maintenance of memory CD8(+) T-cells: up-regulated in these cells, where it generates phosphoenolpyruvate, via gluconeogenesis (By similarity). The resultant phosphoenolpyruvate flows to glycogen and pentose phosphate pathway, which is essential for memory CD8(+) T-cells homeostasis (By similarity). In addition to the phosphoenolpyruvate carboxykinase activity, also acts as a protein kinase when phosphorylated at Ser-90: phosphorylation at Ser-90 by AKT1 reduces the binding affinity to oxaloacetate and promotes an atypical serine protein kinase activity using GTP as donor. The protein kinase activity regulates lipogenesis: upon phosphorylation at Ser-90, translocates to the endoplasmic reticulum and catalyzes phosphorylation of INSIG proteins (INSIG1 and INSIG2), thereby disrupting the interaction between INSIG proteins and SCAP and promoting nuclear translocation of SREBP proteins (SREBF1/SREBP1 or SREBF2/SREBP2) and subsequent transcription of downstream lipogenesis-related genes.
Synonyms: PEPCK-C; PEPCK1; PCKDC; PEPCKC
Tractability: Small molecule: a structure with a bound ligand is known; a high-quality ligand is known; it has a high-quality binding pocket; it belongs to a druggable protein family. PROTAC: UniProt records ubiquitination sites on it; ubiquitination databases record sites on it; a small molecule that binds it is known.
Target class: Enzyme; Lyase
Safety:
Unwanted effects reported when the protein is acted on. In parentheses: how it was acted on, where the effect was seen, and who reports it.
Accumulation, Liver lipid (inhibition; source: AOP-Wiki)
Gene: Protein-coding gene on chromosome 20 (57,560,573 to 57,568,121, forward strand). Ensembl gene ENSG00000124253.
Subcellular location: Cytoplasm, cytosol; Endoplasmic reticulum
Pathways (Reactome):
Chromatin organization: Interaction of NuRD complexes with transcription factors
Developmental Biology: Transcriptional regulation of white adipocyte differentiation
Drug ADME: Abacavir metabolism
Gene expression (Transcription): FOXO-mediated transcription of oxidative stress, metabolic and neuronal genes
Metabolism: Gluconeogenesis
Signal Transduction: NR1H2 & NR1H3 regulate gene expression linked to gluconeogenesis
Gene Ontology:
Molecular function: carboxylic acid binding; GTP binding; magnesium ion binding; manganese ion binding; phosphoenolpyruvate carboxykinase (GTP) activity; protein serine kinase activity (using GTP as donor); phosphoenolpyruvate carboxykinase activity; purine nucleotide binding
Biological process: cellular response to glucose stimulus; cellular response to insulin stimulus; gluconeogenesis; glucose metabolic process; oxaloacetate metabolic process; peptidyl-serine phosphorylation; positive regulation of lipid biosynthetic process; regulation of lipid biosynthetic process; response to insulin; tricarboxylic acid metabolic process; cellular response to dexamethasone stimulus; glucose homeostasis; glycerol biosynthetic process; hepatocyte differentiation; positive regulation of memory T cell differentiation; response to starvation; glyceraldehyde-3-phosphate biosynthetic process
Cellular component: cytosol; endoplasmic reticulum; extracellular exosome; cytoplasm; mitochondrion
Genetic constraint (gnomAD): Loss-of-function variants: 42 observed, 48.97 expected, observed/expected ratio (o/e) 0.86, 90% interval 0.67 to 1.11. The upper end of that interval is the gene's LOEUF score, 1.11, which puts it in group 4 of 6, group 1 being the genes least tolerant of losing a copy. Missense variants: 771 observed, 832.7 expected, observed/expected ratio (o/e) 0.93, 90% interval 0.87 to 0.98. Synonymous variants: 326 observed, 321.67 expected, observed/expected ratio (o/e) 1.01, 90% interval 0.93 to 1.11.
Gene-disease validity (ClinGen):
ClinGen rates the evidence that PCK1 causes each of these diseases.
phosphoenolpyruvate carboxykinase deficiency, cytosolic (autosomal recessive): Definitive. PEPCK1 deficiency is a rare inborn error of metabolism disorder, characterized by the deficiency of the enzyme PEPCK1, one of the enzymes needed for gluconeogenesis, the process by which organisms produce sugars (namely glucose) from non-carbohydrate precursors (such as amino acids).
Homologues: Orthologues: chimpanzee PCK1 (99% identical), macaque PCK1 (98% identical), mouse Pck1 (91% identical), rabbit PCK1 (90% identical), dog PCK1 (90% identical), guinea pig PCK1 (90% identical), rat Pck1 (89% identical), pig PCK1 (86% identical), zebrafish pck1 (74% identical), Drosophila melanogaster Pepck1 (64% identical), Drosophila melanogaster Pepck2 (64% identical), tropical clawed frog pck1 (62% identical), and 3 more. Paralogues in human: PCK2 (71% identical).
Diseases named in the same sentence as PCK1 in open-access papers:
PCK1 is named in the same sentence as 131 diseases in open-access papers, as found by Europe PMC text mining. Sharing a sentence is not in itself a finding about the gene and the disease. The quoted sentences say what the papers report.
Insulin resistance (59 papers, 2013 to 2025). Increased resistance towards insulin, that is, diminished effectiveness of insulin in reducing blood glucose levels. "In the context of Gel-VHH, Pck1 is considered a key mechanism underlying insulin resistance and its modulation of inflammation." (PMID 39811465, 2025). "Overexpression of phosphoenolpyruvate carboxykinase (PEPCK, gene name: Pck1) increases glucose production and predisposes to hyperinsulinism and insulin resistance." (PMID 39063287, 2024). "The PCK1 gene is associated with obesity, insulin resistance, type II diabetes in mammals, and abdominal fat content." (PMID 33815460, 2021). "HCV promotes hepatic gluconeogenesis by significantly up-regulating the transcription of PCK1, leading to insulin resistance and type 2 diabetes in predisposed individuals." (PMID 23923051, 2013). "Furthermore, palmitate-induced insulin resistance in Hepa 1–6 was also associated with increase in glucose production and elevated expression of genes involved in gluconeogenesis- Foxo1, Pck1 and G6pc." (PMID 38745315, 2024). "Recent studies have shown that PCK1 functions as a regulator of hepatic energy metabolism and gluconeogenesis, with its dysregulation linked to metabolic diseases, such as diabetes, obesity, insulin resistance, and tumor development." (PMID 30717766, 2019). "In addition, overexpression of PCK-1 in adipose tissue is shown to cause insulin resistance in HFD fed mice." (PMID 29089532, 2017). "The PCK1 gene is associated with obesity, insulin resistance, and type II diabetes in mammals." (PMID 27506765, 2016). "Overexpression of PCK1 gene in adipocytes may be associated with obesity and insulin resistance." (PMID 34641739, 2021). "Pck1 is a regulator of the energy metabolism and gluconeogenesis in the liver, and its imbalance is related to metabolic diseases, such as diabetes, obesity and insulin resistance, while there is also a certain correlation between PPARγ and Pck1." (PMID 40786039, 2025). "A study indicated that mice with reduced Pck1 expression develop insulin resistance, hypoglycemia, and hepatic steatosis." (PMID 39398341, 2024). "Insulin resistance develops not only in atherosclerotic vascular disease but also in hypertension; therefore, s-PCK1-Ab levels are related to CVD and hypertension." (PMID 37904164, 2023). "Some studies have shown that, in animal experiments, overexpression of PCK1 promoted insulin resistance." (PMID 35893906, 2022). "The PCK1 is reported to be essential for regulating lipid metabolism and glucose homeostasis and for preventing insulin resistance in mice." (PMID 33152221, 2021). "After a seven-day accumulation of intracellular lipids, the development of insulin resistance was detected in spheroids on day 14, as evidenced by the increased expression of PCK1 and PDK4 and by reduced GSK3β phosphorylation." (PMID 35052590, 2021). "It has been reported that the overexpression of PCK1 in type 1 diabetes mellitus leads to increased gluconeogenesis in the liver and kidney, insulin resistance, and hyperglycemia." (PMID 34203686, 2021). "The LS diet increased the expression of genes related to insulin resistance (ApocIII, G6pc, Pck1) and reduced those involved in oxidative capacity (Prkaa1, Prkaa2, Ppara, Lipe) and lipoprotein assembly (Mttp)." (PMID 34202724, 2021). "Greater insulin resistance (increased PCK1 expression and the generation of a proinflammatory profile) and a fibrotic profile (increased α-SMA, TGF-β, and steopontin) have also been reported." (PMID 35052590, 2021). "Increased insulin resistance corresponded with a modest increase in liver gluconeogenic Pck1 expression." (PMID 30409703, 2019). "As a result of insulin resistance, gluconeogenesis is activated, which stimulates the increase in PCK1 and G6PC gene expression." (PMID 31805072, 2019). "PCK1 plays an important role in glucose metabolism, and gene-nutrient interactions on PCK1 modulates insulin resistance in metabolic syndrome subjects." (PMID 28837672, 2017).
Insulin resistance (continued). "GDM rats showed possible insulin resistance as evidenced by high expression of proinflammatory cytokines, PCK-1 and CRP." (PMID 27379252, 2016). "An increasing number of studies have shown that the PCK1 gene plays a crucial role in multiple physiological processes in mammalian species and is involved in obesity, insulin resistance (type 2 diabetes mellitus, T2DM), and the mammary gland." (PMID 23544081, 2013). "Similarly, mice with reduced Pck1 expression develop insulin resistance, hypoglycemia, and hepatic steatosis, indicating the important role of PCK1 in regulating both glucose homeostasis and lipid metabolism." (PMID 36918564, 2023). "Moreover, chronic sodium restriction increased the expression of markers of liver insulin resistance (G6pc and Pck1) and reduced the expression of transcription factors associated with oxidative metabolism (Prkaa2 and Ppara)." (PMID 36978847, 2023). "Therefore, PCK1 expression increases in the presence of insulin resistance." (PMID 37904164, 2023). "According to the report, the excessive expression of PCK1 can result in type II diabetes symptoms, and excessive sugar dysplasia may also lead to the occurrence of metabolic diseases such as insulin resistance and hyperglycemia, indicating that PCK1 is important in glucose homeostasis." (PMID 33919302, 2021). "It was reported that liver-specific overexpression of Pck1 in mice resulted in FBG elevation, lipid deposition, and insulin resistance." (PMID 38201855, 2023). "Under HFD, mice have impaired glucose tolerance and insulin resistance but unaltered levels of the gluconeogenic enzymes G6PC and PCK1." (PMID 33430468, 2021). "Suppression of CEACAM1, GLUT2, and PON1, and elevation of CD36, PCK1, and G6PK were also found to be characteristic in hyperglycemic HepG2 cells compared with normoglycemic cells, suggesting insulin resistance and NAFLD." (PMID 31805072, 2019). "A complete profiling of Leprdb/J mouse livers established that PCK1 and G6PC gene expression is elevated in the setting of type 2 diabetes as a result of insulin resistance." (PMID 31805072, 2019). "Further studies are warranted to understand the mechanisms by which (i) calpain activation promotes PCK-1 gene expression and activity and (ii) CAST overexpression leads to insulin resistance in long term obesity." (PMID 29089532, 2017). "The GDM animal model showed signs of insulin resistance where expressions of both proinflammatory cytokines (IL-6 and TNF-α), PCK-1, and serum CRP level were higher than control." (PMID 27379252, 2016). "Furthermore, inhibition of miR-721 in high-fat diet-induced insulin-resistant mice resulted in restoration of KDM2A levels, concomitantly reducing FOXO1, PCK1, and G6PC expression, attenuating gluconeogenesis, hyperglycemia, and improving glucose tolerance." (PMID 38745315, 2024). "In addition, the inhibition of anaplerosis, the metabolic reactions that generate TCA cycle intermediates, by knockdown of phosphoenolpyruvate carboxykinase 1 (PCK1) also showed protection against hepatic oxidative stress, inflammation, and insulin resistance." (PMID 33530432, 2021). "Insulin resistance will decrease FOXO1 phosphorylation by insulin through PI3K-AKT, which would retain FOXO1 in the nucleus and prevent cytoplasmic ubiquitinoylation and degradation, resulting in increased expression of G6pc and Pck1." (PMID 33672754, 2021). "Furthermore, the higher level of PCK-1 in the GDM model compared to control indicates that lipid metabolism and glucose homeostasis are compromised, leading to insulin resistance." (PMID 27379252, 2016). "Since patients with DM, especially those with insulin resistance, often complicate nonalcoholic fatty liver disease and nonalcoholic steatohepatitis, there is a high chance of PCK1 leaking from live cells, which might produce antibodies against PCK1." (PMID 37904164, 2023).
diabetes (50 papers, 2005 to 2025). "These included proteins expressed by pancreatic islet cells (Ptch1, Disp1, Pck1, and Cacna1e) as well as proteins known to be associated with diabetes mellitus susceptibility or glucose metabolism (Adcy8, Perm1, Sorbs1, and Pla2g6)." (PMID 37934865, 2023). "It is interesting to note in the 2013 study, glucose control was achieved by PK11195 concomitant with an up-regulation of pck1 in a model of pre-diabetes and obesity typically associated with hyperglycaemia." (PMID 33842883, 2021). "Unexpectedly, Pck1, a main control point for gluconeogenesis that has been linked to diabetes and obesity, was significantly upregulated in livers of Mpzl3 ASO animals." (PMID 33991450, 2021). "In another study performed in the same cohort, a relation was found between diabetes and infarcts; however, we were also unable to mediate the PCK1 association by including a model term for cerebral infarctions." (PMID 20574532, 2010). "PCK1 variants have also been suggested to be associated with diabetes, and independently, diabetes has been identified as a risk factor for the development of dementia." (PMID 20574532, 2010). "Furthermore, the two signaling nodes in the inter-organ mechanism of IPF proposed in our study, CALM1/CALM2/CALM3 (in the lung) and PCK1 (in the liver), are both molecularly linked to diabetes." (PMID 38081956, 2023). "PCK1 has been proven to be a candidate genetic marker for the risk of diabetes and obesity." (PMID 32337289, 2020). "Moreover, PCK1 has been demonstrated to be a candidate genetic marker for diabetes and obesity risk, and more recent research implicated this locus in type 2 diabetes (T2D) risk in Chinese, South Asian and Finnish populations." (PMID 30805021, 2019). "PCK1 is a candidate diabetes and obesity gene and the mutations at PCK1 locus could affect the expression of PCK1 in adipose tissues." (PMID 28561770, 2017). "Since diabetes has also been implicated as a risk factor for age-related cognitive decline, we examined whether diabetes mediates the association of PCK1 with cognitive impairment." (PMID 20574532, 2010). "Furthermore, Hmgcs2, Ucp3, and Pck1 are increased and expressed in Akita mice hearts, and these highly interacting DEGs correlate with their cardiac expression and the importance of their functions in numerous signalling pathways associated with cardiomyopathy in diabetes." (PMID 41007634, 2025). "CYP1A1, HHIP (hedgehog interacting protein), AGTR2, CYP2A6, and PCK1 are involved in growth and development of diabetes mellitus." (PMID 38137330, 2023). "Third, diabetes-stimulated CREBH recruitment to the Pck1 gene promoter was diminished in melatonin-fed mice but was significantly restored by silencing Shp." (PMID 37488285, 2023). "PCK1, with its central role in regulating gluconeogenesis and its other secondary function, is essential to survival, as mice without PCK1 suffer from severe hypoglycemia after birth and die; therefore, PCK1 is a candidate diabetes and obesity gene." (PMID 37888683, 2023). "Previous reports showed that PCK1 expression is increased in several obesity/diabetes mouse models, such as ZDF rats and ob/ob and db/db mice, and the disease progression of MAFLD is positively correlated with obesity and type 2 diabetes mellitus." (PMID 36918564, 2023). "For instance, the expression of PCK1, a candidate gene for diabetes and obesity that facilitates gluconeogenesis, was repressed under arsenic exposure in the liver, but revived with the GW4064 supplement." (PMID 37888683, 2023). "PCK1 is the rate-limiting enzyme of gluconeogenesis, and its expression is frequently increased in individuals with metabolic syndrome and diabetes mellitus." (PMID 35586208, 2022). "The insulin resistance signaling pathway is closely related to diabetes, metabolic syndrome and obesity and is also closely related to the activities of phosphoenolpyruvate carboxykinase 1 (PCK1) and solute carrier family 2 member 4/GLUT4 (SLC2A4)." (PMID 35456474, 2022).